MX1 (MX dynamin like GTPase 1)
Diseases named in the same sentence as MX1 in open-access papers (continued):
Sharing a sentence is not in itself a finding about the gene and the disease.
infection (continued). "Our data show up-regulation of several IFN-associated genes, suggesting that type I IFN pathway is activated during DUVV-NL07 infection resulting in an antiviral response (as evident by the increased expression of Mx1 and OAS)." (PMID 29615985, 2018). "Nevertheless, several downstream genes of the type I IFN signaling pathway were elevated, consistent with reports of other New World arenavirus human infection, including Ifi27, Ifi27l2b, Ifi44, Ifi204, Ifit1, Mx1 and Mx2." (PMID 29724035, 2018). "The results showed that the levels of all the mRNA, including those associated with IPS-1, IRF-3, IFNβ, PKR, OAS, Mx1, and MHC class I were upregulated at 24 and 48 h after infection compared to at 2 h after infection." (PMID 28194372, 2017). "Real-time qRT-PCR results showed that the presence of 200 U/mL IFN-β dramatically increased the mRNA levels of ISG15, OAS1, and MX1 in LC, macrophages, and SC at 8 h post-infection." (PMID 28239382, 2017). "We next explored the impact of RIG-I, MAVS and Mx1 overexpression on the expression of innate immune response genes during infection of JH4 guinea pig fetal lung fibroblasts." (PMID 28418930, 2017). "MX1 was also investigated, a cellular protein that is known to target the envelope of certain viruses to block their infection." (PMID 29137231, 2017). "GBP-1 knockdown in cells overexpressing RIG-I resulted in significantly reduced induction of Mx1 mRNA at 12 and 24 hours post infection, whereas Mx1 expression in H5N1 infected cells overexpressing MAVS was not affected by GBP-1 knockdown." (PMID 28418930, 2017). "During infection experiments with ppEndo cells we observed strong MX1 expression not only after infection with Vp447 but also in the non-infected control." (PMID 28290554, 2017). "An example of this is the human Mx protein in which human MxA (corresponding to the Mouse Mx1) was found to confer antiviral activity against infection with single-strand RNA virus, while human MxB was devoid of any antiviral action." (PMID 28066698, 2016). "We confirmed that the transcriptional expression of Mx1 and Ddx58 was increased over time during infection." (PMID 27826541, 2016). "The Mx1 expression reached its peak at 24 h post-infection, whereas Isg15 expression declined from the peak at 6 h." (PMID 27826541, 2016). "By 9–10 days post-infection, the expression of MX1 seems to decrease mildly in Lassa and Marburg infection, but it remains at very high levels compared to the pre-infection baseline." (PMID 27595844, 2016). "SeV-induced expression of IFN-β, CXCL10, Mx1 and CCL5 in OPN-deficient macrophages was also restored upon infection with lentivirus containing the C-terminal fragment of iOPN." (PMID 27026194, 2016). "This gave detectable IFNβ in lung washes, and increased Mx1 transcription in lungs by d1, whereas infection took until d3." (PMID 27223694, 2016). "Expression of IFN-λ and some key ISG (OASL and Mx1) was induced in the early time and reached at their maximum value on day 2 post infection, and then started to decline gradually from day 3 post infection." (PMID 27449021, 2016). "Lentiviral infection of WT iOPN expression plasmid into OPN-deficient macrophages restored SeV-induced expression of IFN-β, CXCL10, Mx1 and CCL5 to the same level as that in WT macrophages." (PMID 27026194, 2016). "To understand how IFN-I and its evasion both control infection outcomes, we used Mx1-cre mice to tag floxed viral genomes in IFN-I responding cells." (PMID 27223694, 2016). "Up-regulation of ISGs such as OAS1, MX1, and the transcriptional regulator ISGF3γ were observed within 24 h of infection in iHLCs." (PMID 25826356, 2015). "High levels of nuclear Mx1 were detectable in the majority of IECs in tissue samples from wild-type and Ifnar1-/- animals already at day 1 post-infection." (PMID 25849543, 2015). "In the chronic phase of infection, levels of Mx1 in the T-cell zone was significantly elevated compared to uninfected controls." (PMID 26360709, 2015).
infection (continued). "IFN-λ1 treatment induced a bimodal MX1 increase with a first peak at 6 h post-infection and a second peak nearly 100-fold higher than basal at 24 h." (PMID 26411318, 2015). "In the three experimentally infected animals, Mx1 staining was elevated at week two post-infection compared to uninfected controls in the T-cell zone." (PMID 26360709, 2015). "One week after infection, we observed a simultaneous increase of BST2 and MX1 transcripts in PBMC compared to pre-infection values, which reached a maximum at 10 days post infection (dpi)." (PMID 26554913, 2015). "To visualize the virus-induced IFN response in the intestinal mucosa in time and space, we immunostained tissue sections from infected suckling mice for reovirus antigen and Mx1 at 1 and 4 days post-infection." (PMID 25849543, 2015). "Our results from the cross-sectional studies suggest an induction of BST2 together with MX1 during the asymptomatic phase of infection." (PMID 26554913, 2015). "The MX1 gene is induced in cells upon infection with HCoV-229E or EV71 at a time point when the type I IFN level is low." (PMID 26694452, 2015). "Because N. caninum is a common pathogen of cattle rather than humans, primary bovine fibroblasts were also infected with Neospora, demonstrating that both human and bovine cells upregulated Mx1 expression following infection." (PMID 24505488, 2014). "The treatment with JAK Inhibitor I was accompanied by a significant decrease in viral replication (as assessed by quantification of M-vRNA) and by a diminished expression of RIG-I, IFNβ, IFNλ1, PKR, and Mx1 transcripts 24 h post-infection." (PMID 24712747, 2014). "To gauge the role of Muc5ac, we treated Mx1-deficient mice that were infected S. mansoni 10 weeks previously with Etanercept or PBS 3 and 1 day before, and also 1 and 3 days after infection with influenza A virus strain PR8 (2000 pfu/mouse)." (PMID 25398130, 2014). "In infected Mx-IFNLR10/0 mice, many scattered Mx1-positive hepatocytes were detected in the liver, with the response being most intense close to infection foci, confirming the ability of hepatocytes to respond to type I IFN." (PMID 24498220, 2014). "Four days after infection, a 5-fold difference was observed, and 6 days after infection the mutant virus was still present in 5 out of 9 Mx1-positive mice with titers up to 2×105 PFU." (PMID 23555271, 2013). "Based upon our data, the effect of Mx1 is minimal at this time post infection, with cis-factors being much more critical in determining the actual transcript levels of various differentially expressed genes." (PMID 22384400, 2012). "The infection also significantly increased mRNA of IFN-stimulated anti-viral genes myxovirus (influenza virus) resistance 1 (MX1), 2′5′ oligoadenylate synthase (OAS), and IFN-stimulated gene 56 (ISG56), as compared to control cells." (PMID 22396727, 2012). "Upon infection, both Mx1 and Mx3 mRNAs showed a down-regulation in A22 cells 4 hours post infection, as observed for IFNs." (PMID 22514610, 2012). "Infection with either GV or NSDV resulted in a significant reduction in IFN-induced Mx-1 promoter activity when compared to uninfected cells." (PMID 22163042, 2011). "Other genes involved in immune response which were up regulated in all time point of infection were Mpa 21, Mx2, Mx1 Phf11, Tgtp, B2 m and Tap1." (PMID 21371334, 2011). "At 20 hours post infection with SC35M-ΔNS1 the Mx1 protein levels in lungs of IL28Rα0/0 mice were about 2-fold lower than in the wild-type animals." (PMID 18787692, 2008). "In contrast, ruxolitinib had a dramatic suppressing effect on STAT1, P-STAT1, and MX1 upregulation when it was added also pre-infection, also resulting in a dramatic increase in VSV protein accumulation, ultimately partially reversing the phenotype of siMETTL3-transfected SUIT-2." (PMID 40214229, 2025).
infection (continued). "Protein–protein interaction network analysis identified several hub genes (Usp18, Stat2, Ifih1, Jun, Irf7, Rsad2, Ifit1, Mx1) that likely play central roles in coordinating the antiviral immune response and immunometabolic regulation across different phases of infection." (PMID 40867782, 2025). "In contrast, we observed a clear induction of the antiviral protein Mx1 in response to infection." (PMID 39968620, 2025). "Infection with VSV also induced MX1 to levels similar to those measured upon pan-IFN treatment." (PMID 38743751, 2024). "Infection of microglia was associated with a sharp increase in CCL2 and CXCL10 chemokine gene expression and the activation of many type I interferon stimulated genes (MX1, ISG15, ISG20, IFI27, IFITM3 and others)." (PMID 38737767, 2024). "Therefore, MX1 expression offers potential to stratify patients for antiviral therapy or infection control interventions." (PMID 39616162, 2024). "This may be attributed to a dampened IFN response at the early stages of SARS-CoV-2 infection, as evidenced by detectable IFN-β and MX1 expression at 48 and 72 h post-infection." (PMID 38675974, 2024). "To explore this relationship among participants in the replicative infection group, we compared MX1 and IFI27 levels with the average expression of a multigene signature (“STAT1 regulated module”) that we had previously derived and validated as a measure of type 1 IFN bioactivity." (PMID 39616162, 2024). "Interestingly, we observed the downregulation of genes such as Tnf-α, Il18, Mx1, Rig1, Pkr, Stat1, Stat2 and Irf9, which appear to be hallmarks of hRSV persistence in contrast to the acute infection." (PMID 39296294, 2024). "Intriguingly, pretreatment of D2-Mx1r/r mice with interferon or with defective interfering particles protects D2-Mx1r/r from severe IAV disease and death, most likely because functional MX1 protein is produced before infection, thus inhibiting the rapid spread of virus in the early infection phase." (PMID 38360537, 2024). "After infection of MX1-KD lentivirus, DSACs showed a prominent increase in cell proliferation ability, which could be confirmed through EdU staining results." (PMID 38066591, 2023). "We observed a large increase in both immunoproteasomal subunits PSMB8 and PSMB10, and the IFN-activated proteins ISG15 and MX1 in serum and in infected cells 3 and 7 days after infection, thus connecting these changes in blood proteins to those after SARS-CoV-2 infection." (PMID 37739942, 2023). "In contrast, BA.5 infection upregulated Cxcl10, Isg15, and Mx-1 expression more than the other Omicron subvariants infection in the lung periphery area, suggesting that BA.5 might provoke severe inflammation, supporting the histopathological data." (PMID 37488344, 2023). "By doing so, we show that detection of the SBV NP five hours after infection in V5-Mx1-expressing cells is as diminished/delayed, as the level of expression of the recombinant V5-Mx1 protein targeted is high, suggesting an Mx1 concentration-dependent gradient in viral NP detection." (PMID 37243140, 2023). "According to the evolutionary arms race hypothesis, evolutionary pressures should have led to the selection of the most appropriate Mx1 antiviral isoforms to resist these infections." (PMID 37243140, 2023). "Furthermore, we identified differential regulation of cytosolic innate defenses including Mx1 and Oas1-3 during infection." (PMID 36678402, 2022). "Decreases in CNS antiviral genes could certainly result in the development of a more robust infection in this compartment, and a recent study noted an inverse correlation in expression of MX1, OAS1, and MX2 expression with SIV RNA levels in the CNS." (PMID 35494221, 2022). "Interestingly, most of the analyzed genes, except for IRF-7 and Mx1, showed higher expression upon infection with A12-LH138L as compared to A12-LLV." (PMID 36387381, 2022).
infection (continued). "Since the Mx1 gene conveys resistance to infection with the Thogoto virus, it is interesting to consider whether KWM/Hym mice also have resistance to Thogoto virus." (PMID 36076303, 2022). "Finally, we demonstrated that infection induces transcription of cytosolic innate immune sensors Mx1, Oas1, and Oas3 in vivo and in vitro." (PMID 36678402, 2022). "In light of this, we tested whether cytosolic sensors Oas1-3 and Mx1 would be upregulated in response to infection." (PMID 36678402, 2022). "During E30 infection, genes associated with the type I IFN signaling pathway (Isg15, Mx1, Mx2, Sp100, Ifit1, Ifit3, Ifih1, Irf7, Irf9, guanylate-binding proteins 2 [Gbp2], and Stat1) and defense response to viruses (Ddx58, Ddx60, Zbp1, Oas2, Nlrc5, and Eif2ak2) were significantly upregulated." (PMID 36147849, 2022). "Interestingly, we found that IL-27 stimulation prior to infection led to a significant increase in Mx1 expression, which was greater than infection alone." (PMID 36678402, 2022). "Western blot analysis also showed that MX1 levels increased significantly at 48 h post-infection." (PMID 34079533, 2021). "In this regard, our citrullinome analysis reveals that a variety of cellular proteins, such as IFITs or Mx1, are significantly less citrullinated upon infection with the AD169ΔIE1 mutant compared to the wild-type virus, implying a central role of IE1 in mediating HCMV-induced citrullination events." (PMID 34162877, 2021). "Given the fact, that the antiviral effects against hvPR8 mediated by ΔNS1 viral are facilitated by an IFN mediated mechanism (Mx1 gene induction), we speculated that ΔNS1 treatment should protect mice from infections by other IFN sensitive viruses." (PMID 34401874, 2021). "Whether the reduced MX1 expression early in the E.H. group determines the more dramatic infection and disease course in this group is unknown." (PMID 34177946, 2021). "Additionally, some of the individual AGMs did exhibit increased expression levels of ISGs, including MX1, earlier during infection." (PMID 32119719, 2020). "Interestingly, ISGs, including IFIT2, CXCL10, RIGI, and Mx1, were also detected very early after infection (4 to 12 hpi)." (PMID 31375585, 2019). "Next, we hypothesized that Mx1-9R treatment induced effective T-cell responses to clear the infection." (PMID 30696001, 2019). "We next measured the viral titers in the lungs of infected mice to test whether pre-infection Mx1-9R treatment reduced the viral burden." (PMID 30696001, 2019). "The IFN-induced Mx1 protein has been shown to have potent antiviral activity against influenza viruses in humans and mice, although overexpression of Mx1 alone in guinea pig cells reduced viral titers in vitro only at 72 hours post infection." (PMID 28418930, 2017). "But, infection of lentivirus containing the N-terminal fragment of iOPN could not increase or restore SeV-induced expression of IFN-β, CXCL10, Mx1 and CCL5 in WT and OPN-deficient macrophages, respectively." (PMID 27026194, 2016). "In addition, a steady increase in MX1 starting at 12 h post-infection and reaching 25-fold, was observed in the IFN-λ1/DENV-2 group." (PMID 26411318, 2015). "In support of this hypothesis, KD of STAT1 prevents CVB-induced MX1 expression in α cells and enables a more active infection with CVB5, as evaluated by higher expression of the enteroviral capsid protein VP1." (PMID 26061776, 2015). "Strikingly, chicken Mx1 RNA levels reached an almost 5,000-fold increase at 24 h of infection." (PMID 25540384, 2015). "Likewise, the expression of the MX1 gene increased during the infection course of HCoV-229E, and was significantly higher in the A549-Sc cells than in the A549-Gi cells." (PMID 26694452, 2015). "Induction of Mx1 in the gut but not the blood of 2 of the highly susceptible animals following the first failed challenge is consistent with a localized infection that was contained within the mucosal compartment." (PMID 24884551, 2014).
infection (continued). "Similarly the transcript expression of RIG-I, IFNβ, IFNλ1, PKR, and Mx1 was significantly decreased (P < 0.001) under JAK Inhibitor I treatment after 24 h of infection." (PMID 24712747, 2014). "Interestingly, the N66S variant was the only virus that was able to spread to the CNS of Mx1 positive mice, leading to detectable viral brain titers 8 days post infection." (PMID 21852950, 2011). "Also, we saw substantial expression of Mx1 mRNA 16 h after infection, even in the presence of M3." (PMID 39601535, 2025). "Indeed, increased levels of MX1 expression in primary human MDMs infected with the R191A Nef HIV-1 CH042 were associated with lower numbers of fully spliced viral tat-rev mRNA levels, a surrogate for productive infection." (PMID 41354661, 2025). "Furthermore, SARS-CoV-2 D614G[Omicron spike] infection resulted in a significantly increased expression of ISGs Mx1, Oas1, and Viperin as well as Cxcl10, while pro-inflammatory mediators Cxcl1, Ccl2, and Il6 were not significantly altered in any group compared to the uninfected mice." (PMID 38742107, 2024). "The infection status of AM-Cd36 was further supported by the transcriptional alterations observed between virus-positive and virus-negative cells in AM-Cd36, of which genes related to “response to virus” (such as Mx1 and Isg15) and “apoptosis” (such as Bax and Foxo3) were upregulated." (PMID 39414783, 2024). "Thus, Mx1 and OAS are also associated with resistance to the infection of H7N9 HPAIVs in chickens." (PMID 36960283, 2023). "Altogether, the absence of NP staining and MX1 upregulation implies that the challenge virus, whether it is the Delta or Omicron BA.1 variant, failed to establish infection in the lungs of Nsp1-K164A/H165A-vaccinated and WA1/2020-convalescent hamsters." (PMID 37296125, 2023). "Furthermore, the restriction of VSV-GFP infection by MX1 is enhanced by additional, STAT1-dependent factors likely elicited by IFN production, further highlighting the utility of a STAT1-deficient screening platform for assessing the antiviral activity of individual ISGs." (PMID 35421191, 2022). "Since Mx1, Oas1, and Oas2 were upregulated in cells that O. tsutsugamushi preferentially targets for replication (endothelial cells and MΦ), future studies utilizing knockdown or genetic deletions of these molecules are needed to delineate their role during infection." (PMID 36678402, 2022). "Importantly, in IFNAR1 deficient cells IL-36β no longer protected against infection and IL-36β did not induce Mx1 expression either." (PMID 31619669, 2019). "Thus, up-regulation of Mx1 by EMF may play an important role in inhibiting infection in EMF pre-and co- treated cells." (PMID 28400751, 2017). "Similarly, infection with ATMUV resulted in robust expression of Mx1 and OASL." (PMID 27449021, 2016). "Notably, the Mx1 gene was highly upregulated during early infection." (PMID 25540384, 2015). "Follicular hyperplasia has never been found to be associated with SIV infection of other natural hosts, and both collagen deposition and chronic increased Mx1 expression (as measured at the protein level), segregate pathogenic and non-pathogenic infection models." (PMID 26360709, 2015). "Indeed, Mx1-deficient mice with chronic schistosomiasis were relatively, but not absolutely protected from an infection with influenza A virus, and the protection was lost after treatment with Etanercept." (PMID 25398130, 2014). "For example, pDCs in the circulation may have been exposed to free virus particles/proteins either directly by the challenge virus or produced by a limited infection in the mucosal compartment that transiently appeared as free virions in the circulation to selectively activate Mx1 and Mx2." (PMID 24884551, 2014).